C14orf180 (chromosome 14 open reading frame 180)
Synonyms: NRAC; C14orf77
Tractability: Antibody: UniProt places it where antibodies can reach, with medium confidence; UniProt predicts a signal peptide or a membrane-spanning region; its Gene Ontology location is reachable by antibodies, with medium confidence.
Gene: Protein-coding gene on chromosome 14 (104,579,550 to 104,590,515, forward strand). Ensembl gene ENSG00000184601.
Subcellular location: Cell membrane
Gene Ontology:
Molecular function: protein binding
Cellular component: plasma membrane
Genetic constraint (gnomAD): Loss-of-function variants: 13 observed, 12.51 expected, observed/expected ratio (o/e) 1.04, 90% interval 0.68 to 1.63. The synonymous counts are far from expectation, so gnomAD's model fits this gene poorly and the ratio says little. Missense variants: 235 observed, 189.91 expected, observed/expected ratio (o/e) 1.24, 90% interval 1.11 to 1.38. Synonymous variants: 112 observed, 81.61 expected, observed/expected ratio (o/e) 1.37, 90% interval 1.18 to 1.61.
Homologues: Orthologues: macaque C7H14orf180 (88% identical), chimpanzee C14H14orf180 (68% identical), mouse A530016L24Rik (38% identical).
Diseases named in the same sentence as C14orf180 in open-access papers:
C14orf180 is named in the same sentence as 6 diseases in open-access papers, as found by Europe PMC text mining. Sharing a sentence is not in itself a finding about the gene and the disease. The quoted sentences say what the papers report.
breast carcinoma (1 paper, 2024). "SLC2A4 and C14orf180 downregulation is linked to poor breast cancer outcomes, with lower expression associated with lower survival." (PMID 39409999, 2024).
squamous carcinomas (1 paper, 2025). "Among the most significantly downregulated transcripts in later stage tumors are DEFB132 (a defensin involved in innate immunity), C14orf180 (an integral plasma membrane protein), TMEM252 (an integral plasma membrane protein), and LINC01537, an LncRNA associated with squamous carcinomas." (PMID 41224793, 2025).
C14orf180 also shares sentences with these, for which no sentence is quoted: liver cancer (1 paper); lung disease (1); Obesity (1); tumor (1).